RNU1-46P (RNA, U1 small nuclear 46, pseudogene)
Gene: Small nuclear RNA gene on chromosome 18 (51,283,733 to 51,283,896, reverse strand). Ensembl gene ENSG00000207154.
Homologues: Orthologues: chimpanzee U1 (97% identical), macaque U1 (91% identical), pig U1 (79% identical), rabbit U1 (74% identical), mouse Gm22456 (66% identical), mouse Gm23850 (65% identical), rat U1 (65% identical). Paralogues in human: RNU1-89P (86% identical), RNU1-1 (85% identical), RNU1-11P (85% identical), RNU1-2 (85% identical), RNU1-27P (85% identical), RNU1-28P (85% identical), RNU1-3 (85% identical), RNU1-4 (85% identical), RNVU1-18 (85% identical), RNVU1-29 (85% identical), RNVU1-7 (85% identical), U1 (85% identical), and 134 more.